TMEM181 (transmembrane protein 181)
Description:
Mediates action of cytolethal distending toxins (CDT), which are secreted by many pathogenic bacteria. Expression level of TMEM181 is rate-limiting for intoxication.
Synonyms: GPR178; KIAA1423
Tractability: Antibody: UniProt predicts a signal peptide or a membrane-spanning region. PROTAC: ubiquitination databases record sites on it.
Gene: Protein-coding gene on chromosome 6 (158,536,436 to 158,635,435, forward strand). Ensembl gene ENSG00000146433.
Subcellular location: Membrane
Subcellular location (Human Protein Atlas): Vesicles; Golgi apparatus
Gene Ontology:
Molecular function: toxic substance binding
Cellular component: membrane
Genetic constraint (gnomAD): Loss-of-function variants: 31 observed, 63.51 expected, observed/expected ratio (o/e) 0.49, 90% interval 0.37 to 0.66. The upper end of that interval is the gene's LOEUF score, 0.66, which puts it in group 2 of 6, group 1 being the genes least tolerant of losing a copy. Missense variants: 557 observed, 559.4 expected, observed/expected ratio (o/e) 1, 90% interval 0.93 to 1.07. Synonymous variants: 233 observed, 220.18 expected, observed/expected ratio (o/e) 1.06, 90% interval 0.95 to 1.18.
Homologues: Orthologues: chimpanzee TMEM181 (99% identical), dog TMEM181 (96% identical), pig TMEM181 (94% identical), guinea pig TMEM181 (94% identical), rat Tmem181 (93% identical), mouse Tmem181a (92% identical), rabbit TMEM181 (91% identical), tropical clawed frog tmem181 (79% identical), macaque TMEM181 (79% identical), zebrafish tmem181 (73% identical), Drosophila melanogaster CG13409 (50% identical).
Diseases named in the same sentence as TMEM181 in open-access papers:
TMEM181 is named in the same sentence as 5 diseases in open-access papers, as found by Europe PMC text mining. Sharing a sentence is not in itself a finding about the gene and the disease.
TMEM181 shares sentences with these, for which no sentence is quoted: COVID-19 (1 paper); dental caries (1); Diabetes (1); Obesity (1); tumor (1).